ALB (albumin)
Diseases named in the same sentence as ALB in open-access papers (continued):
Sharing a sentence is not in itself a finding about the gene and the disease.
Hypervolemia (32 papers, 2010 to 2025). An increase in the amount of intravascular fluid, particularly in the volume of the circulating blood. "Careful consideration of albumin dosing and administration duration is essential to mitigate the risk of complications, particularly hypervolemia-induced pulmonary issues, in cases of pre-existing hypervolemia or impaired cardiac pumping function." (PMID 38139434, 2023). "It needs to be asked whether serum albumin levels might also cause worsening of COVID-19 pneumonia accompanied by hypervolemia, and whether these levels might have a role in etiopathogenesis." (PMID 35507997, 2022). "In addition, serum albumin was inversely correlated with PPL associated with hypervolemia in patients with high PPL." (PMID 34336874, 2021). "A pilot study using point-of-care ultrasound (POCUS) of the inferior vena cava (IVC) found severe hypervolemia in 20% of patients after intravenous (IV) albumin, despite adherence to current guidelines." (PMID 41704424, 2025). "Because this hypervolemia is partly driven by an oncotic effect, to which albumin is the biggest contributor, the expanded intravascular volume is also often associated with an increase in the plasma protein and plasma albumin content." (PMID 37848829, 2023). "It has been shown that the decrease in BP following exercise, termed as post-exercise hypotension, appears to be the mechanism for a gain of intravascular albumin via the lymph return, which promotes hypervolemia." (PMID 34987588, 2022). "Third, despite its positive effects on survival, there was a simultaneous dose-dependent association between albumin and both prolonged hospital stay and increased risk of ICU transfer, particularly for fluid overload, in patients with ARF." (PMID 26178624, 2015). "Serum albumin levels are also affected by conditions such as hypervolemia." (PMID 35507997, 2022). "The patients who developed fluid overload were treated with mechanical ventilation (70.7% versus 50.8%) (p = 0.003), albumin (74.7% versus 55.2%) (p = 0.003) and corticosteroids (53.5% versus 35.0%) (p = 0.006) more frequently than those who did not develop fluid overload." (PMID 32401993, 2020). "Therefore, impaired liver and renal functions, as well as hypervolemia, are rather theoretical confounders of the preoperative albumin levels in this cohort." (PMID 32351914, 2020). "It has been hypothesized that in human during training, plasma total osmolar and albumin contents increase to maintain constant during plasma volume expansion due to training-induced hypervolemia, which is consistent with our findings in horses." (PMID 31181740, 2019). "Among the significantly different variables between the two OH/ECW groups, LAVI, E/e ́ ratio, and NT-proBNP were positively associated with fluid overload, while the negative association was found for albumin in unadjusted model." (PMID 29630661, 2018). "Albumin may protect the glycocalyx also by reducing hypervolemia." (PMID 32111230, 2020). "For non-diabetic CKD, fluid overload was associated with being female (β = –2.87, P = 0.003), heart disease (β = 2.69, P = 0.04), high baPWV (β = 0.27, P = 0.04), low hemoglobin (β = –1.10, P<0.001), and low serum albumin (β = –5.21, P<0.001) in multivariate analysis." (PMID 25386836, 2014). "While, in patients with hypervolemia, diuretic treatment is of utmost importance, in patients with underfill hypervolemia, excessive diuretic administration without albumin infusion can have serious deleterious consequences (AKI, dyselectrolytemia, etc.)." (PMID 38540182, 2024). "For example, serum albumin is generally a surrogate marker of nutritional status, but serum albumin is decreased by hypervolemia and/or inflammation regardless of nutritional status." (PMID 35299757, 2022).
Hypervolemia (continued). "Higher percentages of overhydration (OH >1L) and lower serum albumin levels [<40g/L (<4g/dL)] were also seen in advanced CKD: more subjects in stage 5 CKD had fluid overload than those in stage 3 and 2 CKD (p<0.001, and p=0.01, respectively), and lower serum albumin versus stage 3 CKD (p=0.02)." (PMID 30894885, 2018). "Together with no changes in the plasma sodium level, osmolality and albumin concentration our data suggested that extra sodium is not accumulating in the peripheral extracellular fluid to produce hypervolemia." (PMID 28720883, 2017). "Noteworthy is that we did not directly measure plasma volume to enable measurements of albumin content rather than concentration; an important implication given the possibility that hypervolemia may have occurred at a higher magnitude in CHO-P group." (PMID 32757065, 2020).
non-alcoholic fatty liver disease (32 papers, 2012 to 2026). "Elevated TG are a characteristic of liver pathologies of different aetiology, clinically defined as non-alcoholic fatty liver disease in which TG accumulate and plasma albumin and protein decrease." (PMID 29316914, 2018). "It is currently unclear whether there is a relationship between the ratio of glycated albumin to hemoglobin A1c (GA/HbA1c) and mortality in individuals diagnosed with nonalcoholic fatty liver disease (NAFLD)." (PMID 38468235, 2024). "Least Absolute Shrinkage and Selection Operator regression identified 14 key predictors, with age, nonalcoholic fatty liver disease Fibrosis Score (NFS), and albumin emerging as the most influential." (PMID 41942372, 2026). "The objective of this study was to examine the correlation between the albumin-corrected anion gap (ACAG) and non-alcoholic fatty liver disease (NAFLD) using data from the National Health and Nutrition Examination Survey (NHANES) 2017–2018." (PMID 40144875, 2025). "The albumin-to-alkaline phosphatase ratio (AAPR) is a newly developed index of liver function, but its association in patients with non-alcoholic fatty liver disease (NAFLD) has not been established." (PMID 33993872, 2021).
triple-negative breast carcinoma (32 papers, 2016 to 2026). An invasive breast carcinoma which is negative for expression of estrogen receptor (ER), progesterone receptor (PR), and human epidermal growth factor receptor 2 (HER2). "Nab-paclitaxel, an albumin-bound nanoparticle formulation of paclitaxel, has emerged as a critical component in the treatment of triple-negative breast cancer (TNBC), particularly in combination with immune checkpoint inhibitors such as atezolizumab." (PMID 41489768, 2026). "Active targeting through receptor‒ligand interactions in albumin-based nanoplatforms offers a sophisticated and highly effective approach for the targeted delivery of anticancer agents in triple-negative breast cancer (TNBC)." (PMID 41489768, 2026). "Addressing these limitations remains central to developing the next generation of multifunctional albumin nanocarriers for targeted triple-negative breast cancer (TNBC) therapy." (PMID 41489768, 2026). "Albumin-based nanoplatforms utilize multifunctional drug loading methods and binding modes that support efficient, targeted delivery of anticancer drugs in triple-negative breast cancer (TNBC)." (PMID 41489768, 2026). "Albumin-based nanoplatforms hold immense promise for targeted drug delivery in triple-negative breast cancer (TNBC); however, their clinical translation is hampered by several critical challenges that must be addressed for improved therapeutic efficacy." (PMID 41489768, 2026). "JBCS guideline recommends atezolizumab in combination with nab-paclitaxel, nanoparticle albumin–bound paclitaxel, as a highly preferred treatment against locally advanced or metastatic triple-negative breast cancer whose tumors express PD-L1." (PMID 40178688, 2025). "The results indicated that atezolizumab plus albumin-bound paclitaxel raised progression-free survival in the intention-to-treat population and the PD-L1-positive subgroup of patients with metastatic triple-negative breast cancer." (PMID 39469651, 2024). "Across all patients, nanoparticle albumin-bound paclitaxel had a numerically higher pCR rate over other taxanes in patients with triple-negative breast cancer." (PMID 36814820, 2023). "We developed a triple-negative breast cancer treatment plan for this case: paclitaxel albumin combined with capecitabine." (PMID 36741314, 2023). "This study aims to investigate the potential prognostic value of fibrinogen-to-albumin ratio (FAR) in patients with triple-negative breast cancer (TNBC)." (PMID 35774393, 2022). "Nano‐immunotherapy regimens have high potential to improve patient outcomes, as already demonstrated in advanced triple negative breast cancer with nanoparticle albumin‐bound paclitaxel and the immune checkpoint blocker (ICB) atezolizumab." (PMID 33552852, 2021). "Atezolizumab, an immune checkpoint inhibitor against programmed death-ligand 1 (PD-L1), combined with nanoparticle albumin-bound paclitaxel has demonstrated remarkable activity in PD-L1 positive metastatic triple-negative breast cancer." (PMID 33613756, 2021). "Promising results were also yielded by the IMpassion130 study, which tested the combination of PD-L1 inhibitor atezolizumab and nano-particle albumin-bound chemotherapy agent nab-paclitaxel in metastatic triple negative breast cancer (TNBC)." (PMID 32245497, 2020). "Hebao Yuan and colleagues pioneered groundbreaking research demonstrating that, compared with conventional taxane formulations, albumin nanoparticle formulations of paclitaxel (Abraxane) fundamentally alter cancer stem cell dynamics in triple-negative breast cancer." (PMID 41489768, 2026). "Molecular and genetic therapeutics delivered via albumin nanoparticles represent a cutting-edge approach for triple-negative breast cancer (TNBC), aiming to address the aggressive nature and therapeutic resistance of this subtype through precise gene modulation." (PMID 41489768, 2026).
triple-negative breast carcinoma (continued). "In addition to these foundational approaches, Fengjie Liu and colleagues developed baicalin-loaded bifunctional albumin nanoparticles (BANPs) to increase the delivery of the natural flavonoid baicalin for the treatment of triple-negative breast cancer (TNBC)." (PMID 41489768, 2026). "The phase III clinical trial of albumin-bound paclitaxel nanoparticles in combination with an anti-programmed death-ligand 1 (PD-L1) antibody for the treatment of metastatic triple-negative breast cancer has notably extended the survival period of patients with favorable safety profiles." (PMID 40877572, 2025). "The IMpassion130 trial demonstrated that adding atezolizumab to nanoparticle albumin-bound (nab)-paclitaxel improved the survival of patients with untreated, advanced, programmed death ligand 1 (PDL1)-positive triple-negative breast cancer (TNBC)." (PMID 32580722, 2020).
Zinc deficiency (32 papers, 2012 to 2026). A deficiency of the essential metal Zinc; an essential cofactor for many enzymes. "The authors of this study also controlled for markers of inflammation, including CRP and albumin, as we did in our study, emphasizing the independent impact of zinc deficiency on unfavorable clinical outcomes, particularly in CD." (PMID 41228451, 2025). "A prior study demonstrated that serum albumin concentrations improved following zinc supplementation in individuals with severe zinc deficiency." (PMID 40344157, 2025). "It is worthy to mention that albumin is the main carrier of zinc in the body; thus, inadequate albumin can lead to zinc deficiency by affecting its transport." (PMID 40400889, 2025). "Upon multivariate analysis, predictors of IBD-related hospitalization were zinc deficiency (OR 2.42, 95% CI 1.07–5.48, p = 0.03) and low albumin (OR 9.03, 95% CI 3.38–24.15, p < 0.001)." (PMID 41228451, 2025). "Median FCP levels were also significantly higher in the zinc deficiency group (660 vs. 177, p < 0.001) while the median albumin levels were significantly lower in the zinc deficiency group (35.2 vs. 43.3, p < 0.001)." (PMID 41228451, 2025). "Due to the granular data available on our cohort, we were able to attempt to control for markers inflammation including CRP and albumin while analyzing the impact of zinc deficiency on clinical outcomes." (PMID 41228451, 2025). "More than 80% of zinc is carried by albumin; therefore, any liver disease, acute or chronic, which causes protein underproduction can lead to zinc deficiency." (PMID 39189285, 2024). "The intervention for zinc deficiency prevention through the development of a comprehensive assessment tool including greater risk factors (serum albumin concentration and TGDs) should be implemented in clinical practice." (PMID 36678192, 2023). "In the present study, serum zinc deficiency was associated with aorta stiffness independent from serum albumin levels." (PMID 36607966, 2023). "It is worth noting that advanced age, low BMI, and low albumin levels, which are significant predictors of zinc deficiency, overlap with the common characteristics of frailty." (PMID 38068792, 2023). "In patients with CLD, zinc deficiency occurs due to decreased albumin synthesis, impaired intestinal absorption, increased urinary excretion of zinc associated with port-systemic shunt, and poor oral intake." (PMID 36432541, 2022). "In obese patients before bariatric surgery, there were gender differences in globulin, sodium, microalbuminuria; Age group analyses revealed that older people (≥50) were more likely to exhibit albumin, globulin, and zinc deficiency." (PMID 34322512, 2021). "There were significant associations of albumin concentration, marital status, and past pregnancy history with severe zinc deficiency." (PMID 34927136, 2021). "Patients on PD are as likely to have zinc deficiency as those on HD because of lower serum albumin and peritoneal loss of protein and zinc." (PMID 32183286, 2020). "Age, body mass index, and serum albumin level were identified as independent predictors of zinc deficiency in the PD group by multivariate analysis." (PMID 32183286, 2020). "Zinc deficiency also correlated with male gender (p < 0.001), low albumin (<3.5 g/dL) (p=0.001), and elevated CRP (≥0.5 mg/dL) (p=0.001)." (PMID 30405910, 2018). "This pilot study did not identify a statistically significant positive prevalence of zinc deficiency and corresponding low albumin level in patients with gastric and pancreatobiliary cancers at diagnosis or after receiving chemotherapy." (PMID 30018840, 2017). "In a logistic model with relevant predictors, zinc deficiency was positively associated with gender and with serum albumin level." (PMID 24367556, 2013).
Zinc deficiency (continued). "In the CD cohort, only low albumin was associated with hospitalizations (p < 0.001) and ER visits (p = 0.003), while zinc deficiency was independently associated with surgeries in CD (p = 0.022) and IBD-related complications (p = 0.014), as indicated from the multivariate analysis." (PMID 41228451, 2025). "Additionally, patients with zinc deficiency had significantly lower mean (SD) blood concentrations of albumin (3.3 g/dL [0.7] vs. 4.0 g/dL [0.5]; p < 0.001) and haemoglobin (10.8 g/dL [2.0] vs. 13.1 g/dL [1.9]; p < 0.001) than the control group." (PMID 40344157, 2025). "Should albumin be the predominant zinc carrier in the circulation, albumin supplementation may play an important role in treating zinc deficiency." (PMID 38367035, 2024). "Furthermore, older age, lower BMI, and a lower serum albumin levels were independent predictors of zinc deficiency in patients on PD." (PMID 32183286, 2020). "In a logistic regression model, albumin and gender were significant predictors of zinc deficiency." (PMID 24367556, 2013). "The very low zinc levels could be explained by pre-existing zinc deficiency, redistribution of zinc to the liver in response to pro-inflammatory cytokines, and low albumin concentrations." (PMID 22316073, 2012). "In addition, zinc deficiency is likely to be accompanied by a decrease in serum albumin levels." (PMID 39156469, 2024). "In addition, zinc deficiency (serum zinc level < 60 μg/dL) was observed in about 90% of patients with serum albumin levels < 3.5 g/dL, and in about half of the patients with serum albumin levels between 3.5 g/dL and 4.0 g/dL." (PMID 36432541, 2022). "As in our study, zinc deficiency was associated with the female sex, high CRP values, and low albumin levels." (PMID 41228451, 2025). "IBD-related complications were more common in patients with CD subtype (p = 0.041), perianal CD (p = 0.011), zinc deficiency (p < 0.001), high CRP (p < 0.001), high FCP (p = 0.026), and low albumin (p < 0.001)." (PMID 41228451, 2025). "Zinc is carried predominantly by albumin and alpha-2-macroglobulin, and poor protein absorption due to pancreatic proteolytic enzyme deficiency, regardless of its cause, can lead to zinc deficiency." (PMID 39189285, 2024). "Therefore, both CRP and serum albumin have been reported to be associated with elevated CRP, IL-6, TNF-α, IL-1β, and zinc deficiency." (PMID 30941358, 2019). "We conclude that the different levels of albumin in the current patient and control groups cannot fully explain the large difference in the prevalence of zinc deficiency." (PMID 24367556, 2013).
inflammatory bowel disease (31 papers, 2015 to 2026). A spectrum of small and large bowel inflammatory diseases of unknown etiology. "Some studies have shown an association between C-reactive protein (CRP)-albumin ratio (CAR) and prognosis in patients with inflammatory bowel disease (IBD), but evidence regarding the association between CAR and UC remains limited." (PMID 35094678, 2022). "The aims of this study were to evaluate the C-reactive protein/albumin ratio (CRP/ALB), inflammatory markers, and parameters from the complete blood count (CBC) in patients with inflammatory bowel disease (IBD) and their associations with disease activity." (PMID 32655630, 2020). "Furthermore, it has been demonstrated that when added to feces, albumin is degraded within a few hours; the albumin concentration in the gastrointestinal tract of patients with inflammatory bowel disease (IBD) is even lower than in healthy individuals." (PMID 39125595, 2024). "In human medicine, the C-reactive protein-albumin ratio (CRP/ALB) has been used in emergency medicine, oncology and gastroenterology, with a high discriminative capacity for active inflammatory bowel disease (IBD)." (PMID 36766371, 2023). "In inflammatory bowel disease (IBD), an inverse relationship between serum albumin levels and clearance of ADA and IFX was found." (PMID 36986627, 2023). "The objective of our study was to externally validate the value of the fibrinogen-to-albumin ratio (FAR), a new biomarker used to identify active inflammatory bowel disease (IBD)." (PMID 40046919, 2025). "Our objective was to determine if patients who later develop inflammatory bowel disease (IBD) show signs of increased inflammatory activity in plasma measured with high sensitivity C-reactive protein (CRP), calprotectin, and albumin before the clinical onset of IBD." (PMID 36777274, 2021). "Significantly, we also verified a negative correlation between the levels of albumin (ALB) in the bloodstream, a potential indicator of inflammatory bowel disease (IBD), and the levels of ZDHHC6 in the colon." (PMID 39148124, 2024).